RN7SL74P (RNA, 7SL, cytoplasmic 74, pseudogene)
Gene: Miscellaneous RNA gene on chromosome X (97,341,046 to 97,341,344, forward strand). Ensembl gene ENSG00000265260.
Homologues: Orthologues: chimpanzee Metazoa_SRP (100% identical), macaque Metazoa_SRP (93% identical). Paralogues in human: RN7SL2 (80% identical), RN7SL1 (79% identical), RN7SL3 (78% identical), RN7SL126P (78% identical), RN7SL147P (78% identical), RN7SL509P (78% identical), RN7SL551P (77% identical), RN7SL665P (77% identical), RN7SL88P (77% identical), RN7SL296P (77% identical), RN7SL255P (76% identical), RN7SL49P (76% identical), and 703 more.